RNU2-53P (RNA, U2 small nuclear 53, pseudogene)
Gene: Small nuclear RNA gene on chromosome 15 (53,651,977 to 53,652,123, forward strand). Ensembl gene ENSG00000252066.
Homologues: Orthologues: mouse Gm24840 (53% identical), rabbit U2 (52% identical), macaque U2 (51% identical), rat LOC120098728 (49% identical), pig U2 (47% identical), guinea pig U2 (46% identical), tropical clawed frog U2 (46% identical), guinea pig U2 (44% identical), rabbit U2 (44% identical), tropical clawed frog U2 (44% identical), zebrafish U2 (43% identical), guinea pig U2 (42% identical), and 3 more. Paralogues in human: RNU2-41P (52% identical), U2 (48% identical), RNU2-22P (47% identical), RNU2-28P (47% identical), RNU2-58P (47% identical), RNU2-60P (44% identical), RNU2-24P (44% identical), RNU2-42P (44% identical), RNU2-55P (44% identical), RNU2-56P (43% identical), RNU2-6P (43% identical), U2 (43% identical), and 67 more.